SKA2 (spindle and kinetochore associated complex subunit 2)
Description:
Component of the SKA1 complex, a microtubule-binding subcomplex of the outer kinetochore that is essential for proper chromosome segregation. Required for timely anaphase onset during mitosis, when chromosomes undergo bipolar attachment on spindle microtubules leading to silencing of the spindle checkpoint. The SKA1 complex is a direct component of the kinetochore-microtubule interface and directly associates with microtubules as oligomeric assemblies. The complex facilitates the processive movement of microspheres along a microtubule in a depolymerization-coupled manner. In the complex, it is required for SKA1 localization. Affinity for microtubules is synergistically enhanced in the presence of the ndc-80 complex and may allow the ndc-80 complex to track depolymerizing microtubules.
Synonyms: FAM33A; FLJ12758
Tractability: PROTAC: ubiquitination databases record sites on it.
Gene: Protein-coding gene on chromosome 17 (59,109,857 to 59,155,260, reverse strand). Ensembl gene ENSG00000182628.
Subcellular location: Cytoplasm, cytoskeleton, spindle; Chromosome, centromere, kinetochore
Pathways (Reactome):
Cell Cycle: Amplification of signal from unattached kinetochores via a MAD2 inhibitory signal; EML4 and NUDC in mitotic spindle formation; Mitotic Prometaphase; Resolution of Sister Chromatid Cohesion; Separation of Sister Chromatids
Signal Transduction: RHO GTPases Activate Formins
Gene Ontology:
Molecular function: microtubule binding; protein binding
Biological process: attachment of mitotic spindle microtubules to kinetochore; mitotic metaphase chromosome alignment; mitotic sister chromatid segregation; regulation of microtubule polymerization or depolymerization; chromosome segregation; establishment of meiotic spindle orientation; mitotic cell cycle; spindle assembly involved in female meiosis; cell division
Cellular component: kinetochore; outer kinetochore; SKA complex; spindle microtubule; cytosol; meiotic spindle; spindle
Genetic constraint (gnomAD): Loss-of-function variants: 9 observed, 9.82 expected, observed/expected ratio (o/e) 0.92, 90% interval 0.55 to 1.58. That is too few expected variants to judge how well the gene tolerates losing a copy. Missense variants: 79 observed, 93.23 expected, observed/expected ratio (o/e) 0.85, 90% interval 0.71 to 1.02. Synonymous variants: 35 observed, 32.31 expected, observed/expected ratio (o/e) 1.08, 90% interval 0.83 to 1.44.
Homologues: Orthologues: chimpanzee SKA2 (98% identical), macaque SKA2 (96% identical), pig SKA2 (81% identical), dog SKA2 (79% identical), mouse Ska2 (77% identical), guinea pig SKA2 (76% identical), rat Ska2l1 (72% identical), rat Ska2 (65% identical), tropical clawed frog ska2 (43% identical), zebrafish ska2 (41% identical).
Diseases named in the same sentence as SKA2 in open-access papers:
SKA2 is named in the same sentence as 33 diseases in open-access papers, as found by Europe PMC text mining. Sharing a sentence is not in itself a finding about the gene and the disease. The quoted sentences say what the papers report.
breast cancer (19 papers, 2016 to 2023). A primary or metastatic malignant neoplasm involving the breast. "The member SKA2 was associated with the proliferation, migration, and invasion of cancer cells in patients with breast cancer." (PMID 35095717, 2021). "SKA2 is significantly upregulated in breast cancer tissues and is associated with TNM stage and lymph node metastasis." (PMID 34045512, 2021). "In breast cancer, overexpression of SKA2 was found to be associated with poor prognosis." (PMID 35095717, 2021). "Another study demonstrated that miR-301, the locus of which is in the intron of the SKA2 gene, is responsible for centromere assembly, and that the two genes are co-expressed in primary breast cancer samples." (PMID 36439516, 2022). "MiR-140-3p also suppressed breast cancer cell proliferation, migration, invasion, and glycolysis partially through the circ_0008039-miR-140-3p-SKA2 regulatory network." (PMID 35681442, 2022). "PRR11 and SKA2 gene pair are overexpressed in breast cancer and esophageal carcinoma, which accelerate proliferation, migration, and invasive capabilities." (PMID 34993016, 2021). "Amongst the other highly significant upregulated CR genes by p-value and log2FC, SKA2, MKI67, HJURP, BIRC5, and CCNB1 are upregulated in breast cancer tissues and all five except for SKA2 have been identified as prognostic markers for breast cancer." (PMID 32457901, 2020). "The role of the PRR11 and SKA2 gene pair has been described in various types of cancer, including breast cancer, non-small cell lung cancer, hepatocellular carcinoma and ovarian carcinoma." (PMID 32565988, 2020). "For instance, in breast cancer, miR-301 derived from SKA2 gene, which has an oncogenic action, negatively regulates tumor suppressors such as PTEN." (PMID 32610610, 2020). "Our results revealed that the effect of SPRY4-IT1 on breast cancer cells is at least partially through targetting SKA2." (PMID 30104400, 2018). "Previous study showed that overexpression of SKA2 was observed in breast cancer and lung cancer specimens and its expression was enhanced to cancer cell proliferation." (PMID 29928475, 2018). "Our experiments indicated that the inhibition role of NT21MP in breast cancer is partially achieved through SKA2." (PMID 30104400, 2018). "Taken together, our findings presented that NT21MP can regulate expression level of SPRY4-IT1 by blocking SDF-1α/CXCR4 axis and subsequently, activating SKA2 and playing a key role in breast cancer cell apoptosis." (PMID 30104400, 2018). "Recent evidences showed that overexpression of SKA2 promoted proliferation and human breast cancer progression, whereas SKA2 knockdown in human lung epithelial cells reduced transactivation and suppressed dexamethasone inhibition of proliferation." (PMID 27121316, 2016). "Knockdown of PRR11 and SKA2 inhibited migration and invasion of breast cancer cells." (PMID 37752518, 2023). "SKA2 can mediate the proliferation, migration, and invasion of breast cancer cells through EMT." (PMID 34993016, 2021). "MiR-520d-3p antitumor activity in breast cancer via post-transcriptional regulating SKA2." (PMID 34993016, 2021). "Currently, studies on PRR11 and SKA2 mainly focus on lung and breast cancer; however, the role of PRR11 and SKA2 in ESCC remains unclear." (PMID 32565988, 2020). "To further validate the relationship between SPRY4-IT1 and SKA2 on biological activity in breast cancer cells, we examined SKA2 levels and screened the most effective siRNAs of SKA2 after transfection with SKA2-specific siRNA or a non-targetting control siRNA for 24 h." (PMID 30104400, 2018). "In breast cancer (BC), SKA2 is highly expressed and serves as a useful biomarker in both tumor initiation and progression." (PMID 37180139, 2023).
breast cancer (continued). "To explore the function of SKA2 in breast cancer cells, we first assessed SKA2 proliferation using SRB assays and found that SKA2 knockdown inhibited cell proliferation." (PMID 30104400, 2018). "In the present study, we examined the level amongst SKA2, SPRY4-IT1, and NT21MP, confirming SKA2 was the target gene of SPRY4-IT1, and the regulation of SPRY4-IT1 on biological activity in breast cancer cells was partially achieved through SKA2." (PMID 30104400, 2018). "Due to the direct targeting of miR-140-3p to SKA2, overexpression of SK2 could partially suppress the inhibitory effect of miR-140-3p restoration in breast cancer cells." (PMID 36439516, 2022). "In brief, SKA2 may function as a vital downstream effector of SPRY4-IT1, which potentially mediates its effects on breast cancer tumorigenesis." (PMID 30104400, 2018). "The present study demonstrated that lncRNA SPRY4-IT1 promoted breast cancer cell biological activity, whereas NT21MP could inhibit its effect by SDF-1α/CXCR4 pathway, which was partially through SKA2." (PMID 30104400, 2018). "Although we have demonstrated NT21MP can exert its anti-breast cancer effect by regulating SPRY4-IT1 and SKA2, the specific mechanism has not been further studied." (PMID 30104400, 2018).
depression (9 papers, 2015 to 2025). "Whereas downregulation of SKA2 is associated with depression and suicidal ideation 4, the expression of SKA2 is important for human health to maintain its normal constitutive levels." (PMID 36860919, 2023). "In a study of patients with major depressive disorder of European ancestry, the interaction of FKBP5, SKA2, and NR3C1 genes with CT in SA was analyzed, showing a significant interaction between FKBP5 and CT." (PMID 41300231, 2025).
lung carcinoma (8 papers, 2011 to 2023). "In this study, we further investigated the molecular mechanisms underlying the implication of SKA2 in lung cancer progression." (PMID 36860919, 2023). "SKA2 is a novel cancer-associated gene that plays critical roles in both cell cycle and tumorigenesis including lung cancer." (PMID 36860919, 2023). "Of note, PDSS2 and SKA2 were associated with clinical outcome in that the worst overall survival was observed in lung cancer patients with high expression of SKA2 and low expression of PDSS2 while the best outcome shown in patients with overexpressed PDSS2 and low expression of SKA2." (PMID 36860919, 2023). "As PDSS2 is the rate-limiting enzyme for CoQ10 biosynthesis and the levels of CoQ10B was also suppressed by overexpression SKA2, we then decided to examine the effect of exogenous CoQ10 treatment on lung cancer cell phonotypes." (PMID 36860919, 2023). "To identify the potential downstream target genes regulated by SKA2, we first analyzed a previously published gene expression profiling data of SKA2 knockdown in human lung cancer cell line A549 (E-MEXP-875)." (PMID 36860919, 2023). "Taken together, these findings elucidated that SKA2 promotes lung cancer cell progression at least partially via repressing PDSS2 expression." (PMID 36860919, 2023). "The levels of PDSS2 expression were significantly decreased in lung cancer samples, and lung cancer patients with high expression of SKA2 and low expression of PDSS2 displayed remarkable poor prognosis." (PMID 36860919, 2023). "The results showed that overexpression of SKA2 alone increased lung cancer cell growth and migration, and these effects were completely abrogated by overexpression of PDSS2." (PMID 36860919, 2023). "Taken together, these findings strongly suggested that SKA2 accelerates lung cancer cell development through repression of PDSS2." (PMID 36860919, 2023). "SKA2 also influences proliferation, migration, and invasive capacity of gastric and lung cancer cells." (PMID 33224872, 2020). "Consistently, the elevated expressions of PRR11 and SKA2 in lung cancer are highly correlated with each other as well as with that of NF-Y." (PMID 28257042, 2017). "SKA2 expression is upregulated in lung cancer and involved in the progression of the disease, but it is not known which of the alternatively spliced SKA2 transcripts (with or without exon 3) are, or if they are both, upregulated in lung cancer." (PMID 27380775, 2016). "Transfection of this SSO into HeLa cells, HEK293 cells, and the lung cancer cell line A549 significantly improves SKA2 exon 3 inclusion endogenously and in the minigene." (PMID 27380775, 2016). "In conclusion, this study clearly demonstrated that PDSS2, the first key enzyme for CoQ10 biosynthesis, is a novel downstream transcriptional target of SKA2 in lung cancer cells, and SKA2 represses PDSS2 transcription through the Sp1-binding sites in PDSS2 core promoter." (PMID 36860919, 2023).
lung carcinoma (continued). "PDSS2 displayed tumor-suppressing activity and could abrogate the SKA2-induced cell proliferation and motility in lung cancer cells." (PMID 36860919, 2023). "In addition, SKA2-mediated lung cancer cell aberrant proliferation and migration can be abrogated by exogenous overexpression PDSS2." (PMID 36860919, 2023). "We determined whether SKA2-induced lung cancer cell proliferation and migration depends on its repression of PDSS2 expression." (PMID 36860919, 2023). "In addition, the PRR11 and SKA2 gene pair has been hypothesized as a potential new target for the diagnosis and treatment of lung cancer." (PMID 32565988, 2020). "The expression of this novel transcriptional regulatory axis of SKA2 and PDSS2 also has prognostic value for lung cancer patients, highly suggesting its substantial contribution to human lung cancer progression." (PMID 36860919, 2023). "This novel transcriptional regulatory axis of SKA2 and PDSS2 functionally contributes to human lung cancer progression and is of potential prognostic and therapeutic significances for lung cancer patients." (PMID 36860919, 2023).
esophageal carcinoma (3 papers, 2020 to 2022). A primary or metastatic malignant neoplasm involving the esophagus. "The SKA2 expression level is upregulated in esophageal carcinoma tissues compared with the adjacent normal tissues." (PMID 36439516, 2022).
glioma (3 papers, 2016 to 2021). A benign or malignant brain and spinal cord tumor that arises from glial cells (astrocytes, oligodendrocytes, ependymal cells). "More likely, SKA1 and SKA3 played a more crucial role compared to SKA2 in those identified pathways for gliomas." (PMID 35095717, 2021). "Based on the results, there are much more related genes identified with SKA1 and SKA3, but less genes for SKA2 in gliomas." (PMID 35095717, 2021). "It has been shown that HOTAIR can control the expression of Rab 22a by sponging miR-373 in ovarian cancer, and modify miR-141 in regulating SKA2 in glioma." (PMID 29156804, 2017). "In an approach using a combination of in silico miRNA target prediction and target confirmation by 3′UTR luciferase assays, qRT-PCR and western blotting, we identified SKA2 as a novel target of miR-141 in human glioma cells." (PMID 27121316, 2016). "To investigate the miRNA-related functions of HOTAIR in glioma, we chose miR-141 as a model miRNA for further studies, with a particular focus on the target gene SKA2." (PMID 27121316, 2016). "In conclusion, our findings from the present study strongly suggest the involvement of HOTAIR in abnormal expression of miR-141 mediated by epigenetic modification targeted SKA2 in glioma." (PMID 27121316, 2016). "We further demonstrated that miR-141 inhibited the proliferation, migration and invasion by targeting the 3′-UTR of SKA2 in human glioma cells." (PMID 27121316, 2016). "Clone formation assay demonstrated that miR-141 knockdown promoted clone formation in glioma cells, while cotransfection with si-SKA2 moderated the effect of miR-141 knockdown." (PMID 27121316, 2016). "We measured the expression levels of HOTAIR and SKA2 in 56 human glioma tissues." (PMID 27121316, 2016). "Because HOTAIR could upregulate SKA2, we next examined whether HOTAIR was co-expressed with SKA2 in human glioma samples." (PMID 27121316, 2016). "In addition, the invasion was promoted in miR-141 inhibitor treated glioma cells, while SKA2 knockdown reversed the invasion mediated by miR-141 inhibitor." (PMID 27121316, 2016). "Interestingly, HOTAIR may act as a ‘sponge’ of miR-141, thereby modulating expression of SKA2 in glioma." (PMID 27121316, 2016). "It has been observed that there is a statistically significant overexpression of the mRNA levels of SKA1, SKA2, and SKA3 in tumors as compared to normal tissues of patients with glioma included in the UALCAN database using Wilcoxon rank sum tests (p < 0.01)." (PMID 35095717, 2021). "We found a significant overexpression of the mRNA levels of SKA1, SKA2, and SKA3 in patients with glioma patients." (PMID 35095717, 2021). "Higher expression of SKA1 and SKA3, but not SKA2, was significantly correlated with shorter overall survival of patients with glioma." (PMID 35095717, 2021). "The mRNA levels of SKA1, SKA2, and SKA3 were significantly upregulated in gliomas." (PMID 35095717, 2021). "The expression of SKA2 did not correlate with OS of patients with glioma." (PMID 35095717, 2021). "However, the clinical value of SKA complex (SKA1, SKA2, and SKA3) as a prognostic biomarker in gliomas has not been investigated fully." (PMID 35095717, 2021).
mental disorder (3 papers, 2015 to 2024). A disease that has its basis in the disruption of mental process. "Further work will be necessary to distinguish the degree to which SKA2 is specific to suicide biology or more broadly affects other HPA axis-associated mental disorders such as PTSD." (PMID 26305478, 2015). "Notably, single nucleotide polymorphism and epigenetic marks within the FKBP5 and SKA2 genes have repeatedly been associated with stress-related psychiatric diseases including major depressive disorder (MDD) and PTSD as well as suicide risk." (PMID 38528004, 2024).
post-traumatic stress disorder (3 papers, 2018 to 2024). An anxiety disorder precipitated by an experience of intense fear or horror while exposed to a traumatic (especially life-threatening) event. "Single nucleotide polymorphisms and DNA methylation within the SKA2, as well as gene expression alterations, have been associated with posttraumatic stress disorder and suicide risk in human patients." (PMID 38528004, 2024). "SNP rs9898916 is involved in the regulation of SKA2 whose methylation is associated with decreased prefrontal cortical thickness and greater post-traumatic stress disorder (PTSD) severity among trauma-exposed veterans." (PMID 29378629, 2018). "One study analyzed the methylation of the SKA2 gene in patients with post-traumatic stress disorder." (PMID 37190549, 2023). "In addition, hypermethylation of the SKA2 gene has been observed in patients with post-traumatic stress disorder and suicidal behavior." (PMID 37190549, 2023).
gastric cancer (2 papers, 2021). A primary or metastatic malignant neoplasm involving the stomach. "SKA2 overexpression reversed the miR-520a-3p-mediated inhibitory effect on the proliferative and invasive capacities of gastric cancer cells." (PMID 34845974, 2021). "In gastric cancer, the expression of SKA2 was found to be regulated by miR-520a-3p, which acted as a tumor suppressor miRNA." (PMID 35095717, 2021).
hepatocellular carcinoma (2 papers, 2020 to 2021). A malignant tumor that arises from hepatocytes. "A previous report revealed that high level of SKA2 accelerated the proliferation, colony-forming, and invasion of hepatocellular carcinoma cells by means of upregulating Wnt/β-catenin signaling." (PMID 34845974, 2021). "SKA2 was highly expressed in hepatocellular carcinoma (HCC) and can be used as a potential tumor promoter for HCC." (PMID 34845974, 2021).